IDH2 (isocitrate dehydrogenase (NADP(+)) 2)
Diseases named in the same sentence as IDH2 in open-access papers (continued):
Sharing a sentence is not in itself a finding about the gene and the disease.
tumor (continued). "NGS analysis of this fragmented biopsy specimen containing approximately 41%‐60% estimated tumor cellularity revealed a KRAS mutation (VAF: 53%) and two IDH2 mutations (VAFs: 13% for p.R140Q and 17% for p.R172M) within different alleles." (PMID 32333643, 2020). "The first drug targeting tumor energy metabolism approved by the US Food and Drug Administration, the isocitrate dehydrogenase 2 (IDH2) enzyme inhibitor enasidenib, also showed encouraging efficacy for treating IDH2-mutated relapsed or refractory AML." (PMID 32373530, 2020). "HER2+ tumours were more likely to have IDH2 protein which is perhaps unsurprising as high grade progressing DCIS and LVI are significantly associated with HER2 positivity." (PMID 31599393, 2020). "Energy metabolism and biosynthetic intermediates such as Alpha-ketoglutarate (αKG) produced through TCA from isocitrate by IDH2 is essential in tumour progression and metastasis." (PMID 31599393, 2020). "The high frequent mutations on the single residue (R132 in IDH1, R172 or R140 in IDH2) have caught broad interest in its function in promoting tumor development." (PMID 31591388, 2019). "This unexpected finding reveals that (R)-2-HG and (S)-2-HG exert antitumor activity in tumor cells with intact IDH2 function." (PMID 31105869, 2019). "Consistent with the patterns observed above, IDH2-R172M reduced the number of tumor colonies by more than 40% compared to IDH2-WT." (PMID 31105869, 2019). "In contrast, IDH2-R172M tumors developed at a slower rate, requiring 50 days to detect a palpable tumor." (PMID 31105869, 2019). "By blocking IDH2, we confirmed that IDH2 is a potential target for the inhibition of tumor cell growth and tumor secretion." (PMID 31455412, 2019). "By blocking IDH2, we investigate IDH2 play an inhibitory role in GH tumor cell growth and tumor secretion." (PMID 31455412, 2019). "The landscape of MLH1−/− tumors is heterogeneous with only a few shared mutations being detectable among different tumor entities (ARID1A and IDH2)." (PMID 31581674, 2019). "KRAS/NRAS mutations are common in ICC tumours and 6–32% of patients also have isocitrate dehydrogenase 1 and 2 (IDH1 and IDH2) gene mutations associated with metabolic changes." (PMID 31795195, 2019). "The IDH2 (R140Q) NRAS (G13R) population shrinks to 8% of the tumor at the same relapse time point at which the triple-mutant IDH2 (R140Q) NRAS (G13R) ASXL1 (G646fs) clone expands to 64%." (PMID 30087104, 2018). "Wild‐type IDH2 participated in reductive carboxylation of glutamine to support redox homeostasis during anchorage‐independent tumor spheroid formation." (PMID 29465809, 2018). "IDH1 and IDH2, the cytoplasmic and mitochondrial isoforms respectively, had lower levels of expression in the tumours derived from mtDNA-depleted cells than GBM100 tumours." (PMID 30208958, 2018). "An alternative approach has been opened since the discovery that all tumor relevant mutations in IDH1 and IDH2 result in a neomorphic enzyme activity ultimately leading to a dramatic increase of intracellular 2HG." (PMID 29499756, 2018). "We propose a MassARRAY (MS)-based test that can identify 1p/19q codeletion using quantitative SNP genotyping and, simultaneously, characterize hotspot mutations in the IDH1, IDH2, and TERT genes in tumor DNA." (PMID 28915660, 2017). "It is well established that an aberrant hypermethylation of tumor DNA can be caused by mutations in epigenetic modifiers such as IDH1, IDH2, TET1, TET2, and SDH-subunits." (PMID 26848979, 2016).
tumor (continued). "The presence in the tumor of a mutation of the IDH1 or, less commonly, IDH2 genes similarly is associated with better response to therapy and longer survival." (PMID 27242937, 2016). "Potent allosteric inhibitors of glutaminase and tumor-specific IDH2 mutants are currently being tested in clinical trials." (PMID 27756303, 2016). "Mutations of IDH1 and IDH2 as well as those in SDH have been observed in numerous cancers and found to cause global epigenetic changes in the tumor." (PMID 26680454, 2015). "Assignment of IDH-mutated (defined by IDH1 R132 or IDH2 R172 mutations), 1p/19q and TERT promoter mutation (defined by C228T or C250T) status in tumours was determined using conventional sequencing and single-nucleotide polymorphism (SNP) array methods." (PMID 26068201, 2015). "For example, in the right kidney, somatic mutations were identified in ARID1A in tumor one (category 2), and in IDH2 in tumor two (category 3)." (PMID 25159823, 2014). "We observed 5-hmC staining primarily on the nuclei of the tumor cells and hepatocytes; IDH2 staining was observed primarily in the cytoplasm of the HCC cells." (PMID 24716838, 2014). "Among the 84 tumor samples with low ATRX mRNA expression, 44 had mutations in either IDH1 or IDH2, while 34 were WT for both genes, indicating a strong association between ATRX mRNA expression and IDH1/2 mutations (P<0.0001, Chi-Square test)." (PMID 24810474, 2014). "In our group, the preliminary experimental results indicated a tumor suppressor role for IDH2 in HCC (unpublished data); however, the expression of mutated IDH2, the mechanisms of IDH2 mutation, and the precise role of IDH2 in HCC remain under investigation." (PMID 24716838, 2014). "A recent research of mutant IDH2 protein shows a compound, AGI-6780, which can inhibit the tumor-associated mutant IDH2/R140Q." (PMID 24995286, 2014). "84% of grade III tumours and 17% of grade IV had IDH1 or IDH2 mutations that conferred a better prognosis in both; MGMT methylation (defined as average value across 16 CpGs ≥ 10%) occurred in 75% of tumours and was also associated with improved survival." (PMID 24952577, 2014). "Our findings indicate that a high expression of 5-hmC and IDH2 predicts comparably less aggressive tumor behavior." (PMID 24716838, 2014). "Another inhibitor of mutant IDH2, AGI-6780, selectively inhibits the tumor-associated mutant IDH2-R140Q." (PMID 24403254, 2013). "As most, if not all, tumor suppressor genes are inactivated by epigenetic silencing, in a wide variety of tumors, we asked if IDH1 or IDH2 carry the epigenetic signature of a tumor suppressor by assessing cytosine methylation at their promoters." (PMID 23267435, 2012). "Though it has not been biochemically or functionally validated, tumor methylation profiling is supportive of this previously uncharacterized IDH2 variant as tumorigenic." (PMID 41736408, 2026). "Multi-omics studies integrated subtyping, tumor-origin hypotheses, and immune landscape characterization, supporting biomarkers such as IDH2, NEUROD1, and EZH2, and highlighting heterogeneity." (PMID 42209957, 2026). "Consistent with previous studies, TET2 and DNMT3A mutations were observed in non‐tumor cells including myeloid or B‐cells, suggesting early founding mutation in a progenitor cell in a subset of cases, but other mutations like IDH2, RHOA, and CD28 appeared to be tumor‐specific." (PMID 40510016, 2025). "Therapeutically, the downregulation of IDH2 may present challenges, as restoring its function could potentially enhance the redox capacity of tumor cells." (PMID 40282990, 2025). "Furthermore, circ_0028826 and IDH2 levels were decreased, and the miR‐758‐3p level was elevated in tumor tissues from the sh‐circ_0028826 group." (PMID 39113352, 2024).
tumor (continued). "Compared to the initial resected tumor specimen, the recurrent tumor possessed a loss of heterozygosity of the 1p, 10q, 17q and 19q chromosomes, as well as a new C228T TERT promoter mutation, while the status of wild-type IDH1/IDH2 was unchanged." (PMID 39590169, 2024). "IDH2 mutations change the splicing effects of mutated SRSF2 and lead to more profound ASEs than single mutations alone, as well as lethal myelodysplasia with proliferative characteristics in vivo and enhanced tumor self-renewal." (PMID 38302461, 2024). "Circulating 2HG may be a surrogate biomarker of IDH1 or IDH2 mutation status in ICC and correlate directly with tumor burden." (PMID 39273177, 2024). "Our study demonstrates that IDH2-deficient macrophages predominantly exhibit the M1 phenotype, with minimal induction of EMT and tumor growth, as evidenced by the in vitro and in vivo tumor models." (PMID 39256649, 2024). "Additionally, IHC staining found that the positive expression rates of IDH2 and Ki67 were apparently reduced in tumor tissues derived from sh‐circ_0028826–transfected A549 cells compared with the sh‐NC groups (scale bar, 100 μm)." (PMID 39113352, 2024). "In addition, circ_0028826 knockdown also regulated IDH2 by targeting miR‐758‐3p to inhibit tumor growth in vivo." (PMID 39113352, 2024). "The number of sequences necessary for statistically significant (p < 0.05, t-test) differentiation between wild-type and variant tumor markers was investigated for IDH1, IDH2, pTERT C228, and pTERT C250, as patient material with confirmed mutations was available." (PMID 39606159, 2024). "Furthermore, studies have demonstrated a correlation between IDH2 and the tumor microenvironment (TME) in patients with nTFHL-AI, suggesting a role for epigenetic mutations in the variation of clinicopathological features." (PMID 38601148, 2024). "Thus, our findings demonstrated that IDH2 is a key component of macrophage polarization in the tumor microenvironment." (PMID 39256649, 2024). "A previously unknown target of D-mannose, IDH2, was identified, which broadens our knowledge about the effect of D-mannose in the context of tumor, especially tumor metabolism." (PMID 38167476, 2024). "The expression level of IDH2 was positively correlated with tumor stage and lymph node stage." (PMID 38238853, 2024). "The IDH1 intronic mutation (c.414+9T>A) was previously reported in this HBL tumor by us; however, no missense mutations were detected in IDH1 and IDH2 genes in this tumor." (PMID 37273678, 2023). "In contrast to IDH1 and IDH2, no tumour-associated mutations for any IDH3 genes (IDH3A, IDH3B and IDH3G) have been reported." (PMID 37296846, 2023). "However, the expression level of IDH2 protein was significantly decreased in the tumor tissues (P < .001)." (PMID 37266610, 2023). "The unique genetic profile (mutations in IDH1, IDH2, ATR-X, 1p/19q deletion) and complexities of the tumor microenvironment (hypoxic conditions, cell-cell/cell-stroma interactions) all contribute to the scientific challenges of constructing high fidelity LGG models." (PMID 37051530, 2023). "This study aimed to identify the levels of 5-hmC, 5-mC, TETl, TET2, TET3, IDH1, and IDH2 in tumor and the adjacent tissues, so as to explore whether the 5-hmC is decreased in HBV-related HCC tissues and, if possible, to explore the associated mechanism." (PMID 37266610, 2023). "In addition to confirming that IDH2 tumours represent the minority group with 14% of cases, we report that they are highly represented in DD CS." (PMID 36042521, 2022). "No recurrent initiating genetic drivers have been reported in the remaining 30% of IDH1/2 wild type (IDHwt) cases, although these tumours have been reported to exhibit different methylation profiles compared to IDH1 and IDH2-mutant tumours, hereafter referred to as IDH1 and IDH2 tumours." (PMID 36042521, 2022).
tumor (continued). "KDELR3 was mainly expressed in tumor cells, IDH2 was mainly expressed in endothelial cells, S100A6 was mainly expressed in photoreceptor cells, ITPA was mainly expressed in endothelial cells and tumor cells, PARP8 was mainly expressed in T cells, and APRC1B was mainly expressed in endothelial cells." (PMID 35242144, 2022). "We therefore postulate that the patient’s acute presentation may have provided the hypoxic stimulus to slow tumour growth via the compromised metabolic capacity of the mutant IDH1 allele, possibly mitigating the effects of the concurrent mutant IDH2 allele." (PMID 36286062, 2022). "Indeed, analysis of tumor tissues also revealed a major increase of α-KG by fivefold in the tumor xenografts with IDH2 knockdown, indicating that this occurred both in vitro and in vivo." (PMID 35313945, 2022). "However, utilising the larger numbers available in this study, we found 3468 differentially methylated probes (DMPs) across IDH1 and IDH2 tumours, excluding DD CS (n = 31, p = 0.002)." (PMID 36042521, 2022). "Interestingly, profiling of the left-sided tumor manifestation revealed a fundamentally different profile: This tumor showed IDH1 and IDH2 wildtype and TERT C228T promoter mutation." (PMID 35018523, 2022). "Because IDH1/2 mutations maintain through tumor recurrence, the secondary tumor with IDH1/2 wild-type was no recurrence from the primary tumor with IDH2 mutation but was a de novo tumor that was most likely to be related to the previous exposure." (PMID 35505351, 2022). "Furthermore, the high incidence of TERT mutations and TERT promoter methylation in high grade IDH2 tumours, suggests that these events, through activation of telomerase, have prevented the senescent phenotype and bring about high-grade IDH2 tumours." (PMID 36042521, 2022). "Abnormal histone and DNA methylation are emerging as a common feature of tumours with IDH1 and IDH2 mutations and may cause altered stem cell differentiation and eventual tumorigenesis." (PMID 35975235, 2022). "Previous studies of CS have treated IDH1 and IDH2 tumours as one group." (PMID 36042521, 2022). "However, the reductive carboxylation catalyzed by IDH1 and IDH2 only occurred in anchorage-independent tumor cells, cells with altered mitochondria, or located in hypoxic niches." (PMID 34764443, 2022). "He relapsed again on the 21 month and was refractory to treatment with venetoclax—DEC and Gilteritinib monotherapy while the bulk tumor sequencing no longer detect any FLT3-ITD or IDH2 mutation." (PMID 35563039, 2022). "This would account for the comparatively lower frequency of IDH2 tumours." (PMID 36042521, 2022). "Interestingly, the level of IDH2 knockdown seemed to be correlated with the degree of tumor growth retardation." (PMID 35313945, 2022). "We also found that methylation profiles distinguish IDH1- from IDH2-mutant tumours." (PMID 36042521, 2022). "Therefore, although initially suspected to have tumour suppressive function, IDH1 and IDH2 are both oncogenes, encoding oncogenic enzymes: the mutant enzymes catalyse neomorphic reactions with the resultant d-2-HG product." (PMID 36286062, 2022). "However, some CRGs with CNV loss, such as IDH2, MTHFD1L, and ABCE1, showed upregulated mRNA expression, while other CRGs with CNV gain, such as TPK1, showed downregulated mRNA expression between tumor and normal samples." (PMID 36505852, 2022). "Our results showed higher levels of IDH2 in tumor tissue of mCRC, which could be an attempt to compensate for its lower native enzymatic activity compared with its non-tumor counterpart." (PMID 35205159, 2022).
tumor (continued). "Based on the finding that TERT leads to different outcomes in IDH1- and IDH2-mutant tumours, we propose that genetic testing for IDH1, IDH2, and TERT promoter mutations in the context of other clinical factors, could be useful in patient stratification." (PMID 36042521, 2022). "Together with our previous studies showing that IDH1 hotspot mutations are intrinsically tumor suppressive, these findings may provide an explanation for the rare occurrence of IDH1 and IDH2 hotspot mutations in human cancer." (PMID 34440884, 2021). "In CGGA datasets, we adjusted clinical factors such as age, gender, tumor grade, race, IDH2, and X1p19q2, the multivariate Cox regression results also demonstrated that radiosensitivity-related risk score was an independent prognostic factor for LGG (CGGA693: HR:1.726, 95%CI: 1.195-2.493, p=0.004." (PMID 34395274, 2021). "One of these tumours (ID3) also harboured the rare IDH2 pArg172lle mutation which our ddPCR assay was not designed to detect: the other two tumours (ID24 and ID38) were WT for IDH1 and IDH2 mutations." (PMID 34528398, 2021). "Tumor-derived IDH1 and IDH2 mutations not only simultaneously lose their normal catalytic activity: the production of α-ketoglutarate (α-KG) from the convertion of isocitrate, but also gain a neomorphic enzymatic activity: the reduction of α-KG to D-2-hydroxyglutarate (D-2-HG)." (PMID 34079802, 2021). "We provide further evidence that screening for the presence of IDH1‐ and IDH2‐mutant molecules in plasma from patients with central cartilaginous tumours leads to a more accurate grade and prognosis, when interpreted in the context of imaging and anatomical site, than currently provided." (PMID 34528398, 2021). "For instance, IDH2 is a dual regulator of cancer bioenergetics and tumor cell motility, which reprograms mitochondrial dynamics to differentially adjust energy production or promote tumor cell invasion in response to microenvironment conditions." (PMID 33455080, 2021). "The tumor tissue from the patient exhibited strong immunopositivity for the IDH2 mutant enzyme." (PMID 34616365, 2021). "In tumours derived from sh-IDH2-transfected cells, the IDH2 expression was significantly decreased." (PMID 32367071, 2020). "Similar to human tumor cells, TF-1(IDH2/R140Q) cells were known to produce high levels of D-2-HG." (PMID 32245484, 2020). "Similarly, results in IBC showed that a high IDH2 expression was associated with criteria of aggressive behaviour including LVI, larger tumour size, higher grade and poor NPI." (PMID 31599393, 2020). "IDH2 high expression might enhance HER2 signalling pathways that can have effect on the tumour microenvironment to support the growth of the tumour cell, stimulating invasion, LVI and metastasis in BC." (PMID 31599393, 2020). "This may imply that IDH2 could potentially re-programme the metabolic pathways in BC and support tumour cells to survive and indicate its prognostic significance in BC." (PMID 31599393, 2020). "Whereas overall SDHB and IDH2 were moderately correlated in the tumor (Spearman, ρ = 0.37, adj." (PMID 32323921, 2020). "Mice in the sh-IDH2 + R group had lower tumour volumes than those in the sh-NC + R group." (PMID 32367071, 2020). "Thus, the isocitrate dehydrogenase status, such as IDH-1 and IDH-2 mutations, and ATRX mutation or loss and tumours with 1p19q co-deletion has been associated with better prognosis." (PMID 32411235, 2020). "When present, IDH2 was expressed in the cytoplasm of epithelial tumour cells." (PMID 31599393, 2020). "Whereas none of the Mongolian HCC tumor samples was found to carry mutations in IDH1 or IDH2, we observed a subset of 9 samples in the Mongolian cohort that appears to carry TCGA’s IDH-like gene signature." (PMID 32873799, 2020). "In addition, the Bliss independence model showed that radiation and IDH2 knockdown induced synergistic inhibition in cell viability and tumour growth." (PMID 32367071, 2020).